CTLA4 (cytotoxic T-lymphocyte associated protein 4)
Diseases named in the same sentence as CTLA4 in open-access papers (continued):
Sharing a sentence is not in itself a finding about the gene and the disease.
tumor (continued). "In pancreatic cancer high LAG-3 expression on tumor-infiltrating lymphocytes is strongly connected with PD-1 and CTLA-4 expression." (PMID 36077354, 2022). "Here, the ICI treatment, consisting of anti-CTLA-4 and anti-PD-L1, appeared to delay tumor growth in some of the mice, whereas many tumors showed primary resistance to the treatment." (PMID 35631632, 2022). "Immune checkpoint inhibitors are tumor immunotherapy drugs that activate the immune system to fight tumor cells by blocking checkpoint receptors, primarily including CTLA-4 and PD-1 or its main ligand PD-L1." (PMID 36147250, 2022). "It was discovered that IP-score was closely associated with PDCD1, CD274, CTLA-4, and LAG3 expression levels in urinary solid tumours, indicating that IP-score was closely associated with tumour escape and immune depletion." (PMID 36700205, 2022). "Cancer cells producing ligands for the immune checkpoint molecules PD-1 and CTLA-4 is an important mechanism of tumour immune resistance." (PMID 35017553, 2022). "CXCR3-dependent anti-tumor efficacy and upregulation of its ligands in mouse and human tumors were observed following PD-1/CTLA-4 checkpoint blockade." (PMID 36132332, 2022). "Immune checkpoint blockade including anti-PD-1/PD-L1 and anti-CTLA-4, designed to amplify endogenous anti-tumor T cell responses, has showed much success in certain cancers, such as melanoma and non-small cell lung cancer." (PMID 35920986, 2022). "The high-risk patients were accompanied by significantly increased expression of immune checkpoint molecules (including PD-1, PD-L1 and CTLA4) and increased tumor tolerant immune cells, but significantly decreased tumor mutation burden (TMB)." (PMID 36686809, 2022). "Emerging studies have suggested that beyond expressing ligands for co-inhibitory receptors, tumour cells can also express co-inhibitory receptors such as CTLA-4 and PD-1." (PMID 35265944, 2022). "The team transformed high-copy plasmids carrying anti-PD-L1 antibodies and anti-CTLA4 antibodies into engineered E. coli to achieve controllable expression of PD-L1 and CTLA4 antagonists in tumor sites." (PMID 35757741, 2022). "We reported a practical strategy that can facilitate more safe and efficient tumor growth inhibition by means of P407-mediated PDT in combination with CTLA4 and PD-L1 blockade." (PMID 35974207, 2022). "Tumor volume was significantly reduced in breast, colorectal, and pancreatic cancers by the ascorbate anti-PD-1 and anti-CTLA-4 combinations." (PMID 36072595, 2022). "Our data suggested that, while anti-CTLA4-mediated-specific anti-tumor response was maintained by NFAT5 knock out, non-tumor-specific (generalized) salt-mediated NLRP3 pro-inflammatory responses were abrogated by NFAT5 knock out." (PMID 35741331, 2022). "Remarkably, a synergistic activity was highlighted with anti-CTLA-4 agents thus triggering an increase in complete tumor regression from 20 to 80%." (PMID 35785199, 2022). "Immunotherapy, as a tumor therapy, had been validated in a variety of tumors, among which CTLA4 and PDCD1 were the most studied." (PMID 35126519, 2022). "James P. Allison worked in the development of an anti-CTLA-4 blocking antibody to counteract tumor-induced immunosuppression, and Tasuku Honjo’s work played a critical role in the development of the anti-PD-1 blocking antibody." (PMID 36009389, 2022). "Further treatment with the anti-CTLA-4 clone 9H10 to deplete Tregs in addition to anti-PD-1 saw a complete response at both the subcutaneous and liver tumors in mice with two-site tumor." (PMID 36466910, 2022). "The combination of anti-4BB anti-agonist antibodies, anti-CTLA-4 antibodies, and targeted irradiation has led to a 50 percent increase in tumor-infiltrating lymphocytes and a 50 percent increase in tumor-free survival." (PMID 36146527, 2022).
tumor (continued). "Tregs can inhibit the function of tumor-specific T cells by secreting the inhibitory factors IL-10 and TGF-β and activating the CTLA-4 pathway to promote tumor immune escape." (PMID 36358736, 2022). "In tumors derived from the murine KLN205 cancer cells, sitravatinib significantly reduced the proportion of PD-L1-expressing-MDSCs and tumor-associated macrophages among CD11b+ cells and increased T-cell infiltration (CD3+, CD4+ CD8+, Ki67+ PD-1+ CTLA-4+)." (PMID 35572601, 2022). "In particular, we conclude that treatment with steroid should not begin too early, but also not very late, after immunotherapy began; more precisely, it should start as soon as tumor volume, under the effect of CTLA-4 inhibitor alone, begins to decrease." (PMID 36355837, 2022). "Using a mouse model, we previously reported that peri-tumor injection of a controlled-release hydrogel containing low-dose anti-CTLA-4 produces equal or greater tumor control than does high-dose systemic therapy." (PMID 35621582, 2022). "Considering the important role of immune checkpoint molecules such as PD-1, PD-L1, LAG3 and CTLA-4 in tumor immune microenvironment, the expression levels of these molecules were explored between two groups." (PMID 36505846, 2022). "This approach was noted to affect tumor growth while also demonstrating synergistic properties with the checkpoint inhibitor, anti-CTLA4." (PMID 35214655, 2022). "Given the significance of B cell and NK cell in tumor microenvironment, the regulation of CTLA-4 takes place more narrowly as compared to PD-1, and it enjoys exclusive expression on T cells." (PMID 36612259, 2022). "Combination of IL‐21 with anti‐PD‐1 or anti‐CTLA‐4 therapy in animal tumor models resulted in the augmented intra‐tumoral infiltration of CD8+ T cells, along with their increased proliferation and a higher proportion of effector memory T cells." (PMID 35301813, 2022). "The antigen presentation process is tightly regulated and often blocked by tumour cells via immune checkpoints such as CTLA4 and PD-1, suggesting that the upregulation of antigen presentation is indicative of response to immune checkpoint inhibitors." (PMID 35073851, 2022). "This study provides clear evidence illustrating the fundamental role of IL-2 and IL-2 receptors in the anti-tumor efficacy of CTLA-4 blockade." (PMID 35392976, 2022). "S3 still had the poorest prognosis in TCGA and had high expression levels of immunosuppressive genes, high immune scores, low tumor purity score, as well as the poorest prognosis (CTLA4, TIGIT) in ICGC." (PMID 35124891, 2022). "Immune checkpoint molecules, such as PD-1, PD-L1, HAVCR2, LAG3, and CTLA-4, play an important role in tumor immune evasion." (PMID 36186792, 2022). "Fc-dependent therapeutic efficacy of anti-CTLA-4 has similarly been demonstrated by several groups that observed reduced anti-tumor activity and Treg depletion when the Fc-domain is modified to exhibit lesser or no affinity for FcRs." (PMID 35326731, 2022). "CTLA-4 activity at the tumor site is downregulated by regulatory T-cells in a process known as immune tolerance." (PMID 35160275, 2022). "On the contrary, CTLA-4 expression on tumor cells was recognized as a prognostic factor of poor outcome in breast, pancreatic, and nasopharyngeal cancers." (PMID 35634292, 2022). "For example, targeting CTLA-4 using the NP-CTLA-4-siRNA system increased the percentage of tumor-infiltrating CD8 + T cells and decreased the level of Tregs, resulting in amplified activation and antitumor immune responses." (PMID 35189921, 2022). "Anti-CTLA-4, anti-PD-1/PD-L1 antibody and other immune checkpoint inhibitors (ICIs) have greatly improved the results of tumor treatment in clinical practice." (PMID 36189310, 2022). "Inhibitory interactions between TILs and tumor cells are blocked by anti-PD-L1, while the use of anti-CTLA-4 likely both promotes the activation of new tumor-specific T cells and overcomes regulatory T cell inhibitory pathways." (PMID 35154092, 2022).
tumor (continued). "and anti-CTLA-4 showed anti-tumor immune response with increased TH1, DC maturation, and improved tumor control." (PMID 35474500, 2022). "According to additional studies, tumor cells can activate CTLA-4, reduce the number of activated T cells, and prevent the formation of memory T cells, all of which contribute to the tumor immune escape." (PMID 36505462, 2022). "In advanced HCC, immunotherapies have rapidly evolved in recent years, and most of them focused on monoclonal antibodies against CTLA-4 and PD-1 that block immune checkpoints pathways to reactivate the tumor-killing activity of immune cells in the TME." (PMID 36589233, 2022). "The frequency of tumour-infiltrating CD3+CTLA-4+ cells, CD8+PD-L2+ cells and CD8+A2aR+ cells positively correlated with nodal metastasis (p = 0.03, p = 0.03 and p = 0.03)." (PMID 35366537, 2022). "Increasing the pH in tumour tissue improves cytotoxic T lymphocyte infiltration and enhances anti-CTLA-4, anti-PD-1 and chimeric antigen receptor (CAR) T-cell therapy." (PMID 36211409, 2022). "PDL-1 (CD274), PD-1 (PDCD-1) and CTLA-4 were key immune checkpoints involved in tumor immune escape." (PMID 36248992, 2022). "The combination of CTLA-4 and PD-1/PD-L1 monoclonal antibody inhibitor would raise the tumor response rate and generate the synergistic effect." (PMID 36246617, 2022). "In mouse models, repletion of Akkermansia via oral gavage was able to repotentiate tumor response to anti-CTLA-4 and anti-PD-L1 therapy." (PMID 35792976, 2022). "Next, to measure the PK profile of Ipi-WT and Ipi-LALAPG, we performed single dose PK studies at 3 mg/kg in MC38 tumor-bearing human CTLA-4 knock-in (huCTLA-4 KI) C57BL/6 mice." (PMID 35237846, 2022). "But, in several tumors that normally lack IKZF1 expression, overexpression of Ikaros leads to enhanced immune recruitment infiltration and tumor sensitivity to CTLA4 and PD1 inhibitors." (PMID 36353107, 2022). "ICI increases anti-tumor immunity by blocking intrinsic checkpoints that have an inhibitory role in regulating T cell responses, such as cytotoxic T-lymphocyte antigen 4 (CTLA-4) and programmed cell death 1 (PD-1)." (PMID 35296095, 2022). "Checkpoint molecules, such as PD-1 and CTLA-4, induce T-cell anergy upon engagement with their respective ligands, preventing autoimmunity and anti-tumor immunity." (PMID 36248881, 2022). "Blocking CTLA-4 can reverse and restore depleted T cell function, improve proliferation and T cell effector capacity, and inhibit tumour growth significantly." (PMID 36195696, 2022). "Targeting the PD-1:PD-L1 pathway or CTLA-4 to enhance anti-tumor T cell activity, termed immune checkpoint blockade (ICB) therapy, results in striking clinical responses in some tumors including melanoma, renal cell carcinoma, and non-small cell lung cancer." (PMID 35472220, 2022). "Next, we wanted to determine if NFAT5 knock out reduced the anti-CTLA4-mediated anti-tumor activation of CD4+T cells." (PMID 35741331, 2022). "Among these molecules, the importance of CTLA-4 in the inhibition of anti-tumor T cell responses has been subjected to the argument for over a decade." (PMID 35979362, 2022). "The T-cells remain active by blocking the interaction between these ligands and CTLA4, and hence can recognize and kill tumor cells." (PMID 35664731, 2022). "CTLA-4 expression has been found on the surface of tumor-infiltrating macrophages and in neoplastic tissues, where the molecule contributes to the suppression of the specific anti-tumor immune response." (PMID 35158937, 2022). "ICIs are monoclonal antibodies that target PD-1/programmed death ligand 1 (PD-L1) or CTLA-4, reactivating the anti-tumor immune response that is inhibited by the overexpression of these proteins by tumor cells." (PMID 35774996, 2022). "Tumor cells secrete immunosuppressive cytokines (e.g., TGF-b, IL-10, VEGF), drive expression of inhibitory receptors and ligands (e.g., PD-L1/2, CTLA-4) and reduce tumor-specific MHC-I antigens." (PMID 36010965, 2022).
tumor (continued). "Other than the two main immune checkpoints (CTLA-4 and PD-1), there are still other immune checkpoints that are considered as crucial checkpoints in investigating tumor-infiltrating and peripheral Tregs." (PMID 36009853, 2022). "We used a previously developed three-dimensional organotypic culture of patient-derived tumor spheroids treated with anti-CTLA-4 and anti-PD-1 antibodies for this purpose." (PMID 36428963, 2022). "C12_CD4, which mainly comprised CD4+ T cells from tumors, was associated with high gene accessibility for markers of tumor-infiltrating regulatory T cells (Tregs), including TNFRSF18, ICOS and CTLA4." (PMID 35668194, 2022). "It follows that blockade of CTLA4 on T cells would lead to increased activity of cytotoxic T cells and more tumor killing." (PMID 35814431, 2022). "This not only indicates that the pyroptosis score has the potential to predict the efficacy of CTLA4 immunotherapy, but more importantly, it emphasizes the importance of pyroptosis in shaping tumor immunity." (PMID 35053610, 2022). "A higher tumor TIDE prediction score is associated not only with worse ICB response, but also with worse patient survival under anti-PD1 and anti-CTLA4 therapies." (PMID 36159856, 2022). "Using a DNA vaccine encoding B16 NY-ESO-1 T cell epitopes (SCIB2) in combination with regulatory T cells (Treg) depletion, anti-CTLA-4 or anti-PD-L1 produced different T cell responses and effects in tumor growth in mice." (PMID 36145609, 2022). "Recently, a dual variable domain (DVD) immunoglobulin of anti-CTLA4 antibody, that an outer domain (tumor targeting) is connected by serine protease cleavable linkers to an inner domain (CTLA4 targeting), has been developed." (PMID 35222418, 2022). "First, TMB, as a surrogate measure for tumor immunogenicity, predicts responses less reliably in patients treated with combined anti-CTLA-4/PD-1 blockade than with anti-PD-1 monotherapy." (PMID 36175961, 2022). "Recently, immunotherapy has emerged as a promising therapy in the treatment of several solid tumors, and various immune checkpoint molecules, such as PD-1/PD-L1 and CTLA-4, have been found to play an imperial role in tumor immune escape." (PMID 36120364, 2022). "RT also potentiated the clinical efficacy of CTLA-4 blockades by enhancing T cell recruitment and infiltration of the tumour bed, stabilising NKG2D engagement with Rae-1 and increasing TCR clonality within the TME." (PMID 36139665, 2022). "With the development of tumor immunotherapies, two antibodies that targets the T cell checkpoint protein CTLA-4 and PD-1 have shown remarkable clinical effects." (PMID 35046435, 2022). "Programmed death 1 (PD-1) and cytotoxic T lymphocyte-associated protein 4 (CTLA-4) are immune checkpoint proteins that are involved in the initial suppression of T-cell function, playing a crucial role in tumor-mediated immunosuppression." (PMID 36145510, 2022). "Recently, by taking advantage of cutting-edge tumor immunology, scientists have developed novel drugs targeted at ICIs for treating solid tumors, and a few products targeted at CTLA4 and PD-1 have been put into clinical practice." (PMID 36146640, 2022). "In recent years, tumor immunotherapy such as anti-PD-1/PD-L1/CTLA-4 monoclonal antibody and chimeric antigen receptor T-cell (CAR-T) immunotherapy has extensively attentioned as an important part of combined therapy." (PMID 35155577, 2022). "We further revealed that ADAMTS12 expression was positively correlated with immune checkpoint proteins (such as PDCD1, CD274, LAG3, and CTLA4), immunosuppressive genes, chemokines, and chemokine receptors in most tumor types." (PMID 35280819, 2022). "So, using ipilimumab in this event can overcome the effects of CTLA-4 in the tumor microenvironments." (PMID 35632488, 2022). "In murine models of colorectal cancer, CAFs indeed conferred tumor cells resistance to anti-PD-1 treatments by increasing CTLA-4 expression on CD8+ T cells." (PMID 35345849, 2022).
tumor (continued). "Drugs for Tregs targeting CD25 and CTLA-4 and eliminating tumor-related Treg cells include the well-known CTLA-4 antibodies ipilimumab and tremelimumab." (PMID 35582531, 2022). "CD73 mAb combined with CTLA-4 mAb significantly improved the median survival in a tumor metastasis mouse model." (PMID 36159861, 2022). "Numerous studies have implicated tumor-suppressor miRNAs in regulating antitumor immune response within the TME by controlling ICPs such as PD-1, PD-L1, and CTLA-4." (PMID 35189921, 2022). "Recently, a second‐generation HAP evofosfamide (TH‐302) has demonstrated favourable outcomes in combination with CTLA‐4 and PD‐1 blockade by curing more than 80% of tumours in a mouse prostate‐derived model." (PMID 35466515, 2022). "Antibodies targeting PD-1/PD-L1/CTLA-4 are mainly focused in combination with chemotherapy to suppress tumor progression." (PMID 36569674, 2022). "In this study, we analyzed the in vivo anti-tumor effects of 10 different chemotherapies in combination with anti-CTLA-4 and anti-PD-L1 ICB to identify effective chemo‐immunotherapy combinations." (PMID 35634282, 2022). "Although there is limited literature on the combination of CD39 mAb with CTLA-4 mAb, according to the current study, the combination of the two mAbs has great potential in tumor therapy, especially in the treatment of tumor metastasis." (PMID 36159861, 2022). "At the same time, in order to investigate the relationship between type and immune checkpoints, we selected genes related to tumor immune checkpoints: PD-L1, CTLA4, LAG3, PDCD1, PDCD1LG2, and TIGIT." (PMID 36105091, 2022). "In the same year, James Allison’s team at UC Berkeley demonstrated that CTLA-4 activation was one of two opposing signals (the other being CD28 stimulation) integrated by T cells that determine an anti-tumor response." (PMID 35626053, 2022). "Other preclinical studies suggest synergy in IL-3 production and activated CD4+ T-cell tumor infiltration when combining DC vaccines with anti-CTLA-4 therapy." (PMID 36290818, 2022). "The ketogenic diet is associated with anticancer effects, specifically by enhancing antitumor immunosurveillance by reducing the percentage of CD8+ T cells positive for PD-1, CTLA-4, and reducing PD-L1 expression on tumor cells." (PMID 35011741, 2022). "For example, an anti-CTLA-4 monoclonal antibody within the IgG2a subclass depleted Tregs specifically in tumor tissue and thus enhanced antitumor immunity." (PMID 34417572, 2022). "As the representative of ICIs therapy, PD-1/PD-L1 or CTLA-4-based IC blockade therapy has been approved for treating multiple tumor types; however, the efficacy varies in different tumor types." (PMID 35330159, 2022). "While limiting anti-tumor cytotoxic T cells, CAFs can also increase intratumoral Treg recruitment and scRNAseq revealed the upregulation of PD-1 and CTLA4 in Tregs." (PMID 36010899, 2022). "When AU-011 was combined with checkpoint inhibitors, anti-CTLA-4 or anti-PD-1, tumor-free survival rates were increased to 100% and 75%, respectively, and >70% of tumor-free animals were protected from tumor re-challenge after 100 days." (PMID 36016277, 2022). "We observed a similar anti-tumor effect of propranolol as a single agent as well as increased therapeutic efficacy when combined with anti-CTLA4 therapy." (PMID 35017664, 2022). "IPS was able to quantify the determinants of tumor immunogenicity and had predictive value in cancer patients treated with the CTLA-4 and PD-1 blockers." (PMID 36358906, 2022). "The anti-CTLA-4 monoclonal antibody was combined with the mRNA vaccine to enhance the anti-tumor immune response by targeting regulatory pathways in T cells." (PMID 36338731, 2022). "In this study, live animal imaging is used to track anti-CTLA-4 distribution following either systemic injection, targeted peri-tumor injection of a standard hydrogel, or administration of a hydrogel that contains incorporated HAse." (PMID 35621582, 2022).